USP38 (ubiquitin specific peptidase 38)
Diseases named in the same sentence as USP38 in open-access papers (continued):
Sharing a sentence is not in itself a finding about the gene and the disease.
tumor (4 papers, 2020 to 2025). "USP38 can regulate various biological behaviors of tumors and influence tumor initiation and progression." (PMID 40936898, 2025). "Accumulating evidence points towards a complex, dichotomous function, where USP38 can act as either an oncogene or a tumor suppressor, precluding simple classification." (PMID 40936898, 2025). "The potential mechanisms by which USP38 regulates tumor progression are complex, and likely depend on the specific tumor microenvironment." (PMID 40936898, 2025). "Like other members of the USP family, USP38 can regulate FASN protein expression, indicating that USP38 has the potential to indirectly regulate lipid metabolism in the tumor microenvironment." (PMID 40936898, 2025). "The modulation of tumor progression and therapeutic sensitivity by USP38 positions it as an attractive, albeit challenging, therapeutic target." (PMID 40936898, 2025). "Such exploration of tumor universality will provide strong theoretical support for the development of USP38 inhibitors." (PMID 40936898, 2025). "The discovery of the ADAR-USP38 signaling axis deepens our understanding of USP38’s tumor regulation mechanisms and provides new insights for the further development of USP38-targeted inhibitors." (PMID 40936898, 2025). "This review summarizes current research on USP38, highlighting its dual functionality as both an oncogene and a tumor suppressor in various malignancies." (PMID 40936898, 2025). "Our results showed that downregulation of HDAC3 attenuated the increased colony formation and tumor-sphere formation capability induced by downregulation of USP38." (PMID 32404892, 2020). "Oncosphere formation assay showed that downregulation of USP38 significantly facilitated the formation of tumor-spheres while overexpression of USP38 significantly inhibited the formation of tumor-spheres in vitro." (PMID 32404892, 2020). "Therefore, understanding the dual role of USP38 necessitates dissecting these intricate, context-dependent interactions within specific tumor ecosystems." (PMID 40936898, 2025). "It is necessary to validate the activation of the USP38/FASN signaling pathway in more tumor types." (PMID 40936898, 2025). "Moreover, the promotion of PD-L1 expression by USP38 contributes to immune evasion by tumor cells, which undoubtedly increases the potential for resistance to PD-L1 inhibitors." (PMID 40936898, 2025). "Furthermore, the influence of USP38 extends beyond tumor cell-intrinsic effects into the complex milieu of the tumor microenvironment (TME)." (PMID 40936898, 2025). "Based on the protein interaction between USP38 and HDAC3, we believe that the regulation and activation of the USP38/HDAC3 signaling axis may be common across multiple tumor types." (PMID 40936898, 2025). "In the future, we plan to further investigate the regulatory mechanisms of USP38 and develop a highly sensitive and specific serum USP38 detection technology, which will be validated by assessing USP38 protein levels in the serum of healthy individuals and patients with different tumor stages." (PMID 40936898, 2025). "This highlights the complexity of USP38’s role in tumor regulation." (PMID 40936898, 2025). "In conclusion, whether USP38 regulates PD-L1 expression directly or indirectly, it plays a role in the tumor immune evasion process." (PMID 40936898, 2025). "However, it is important to note that under the influence of various factors, such as the tumor microenvironment, cell type, and genetic background, the regulatory role of USP38 in malignancies may exhibit tissue specificity." (PMID 40936898, 2025). "Moreover, overexpression of USP38 is positively correlated with tumor grade and stage." (PMID 40936898, 2025). "Whether USP38 plays roles in tumor immunity requires further explorations." (PMID 32404892, 2020).
tumor (continued). "Subsequent immunoprecipitation and deubiquitination experiments demonstrated that the inhibitory effect of HMX3 on tumor cells is USP38-dependent: USP38’s deubiquitinating activity enhances HMX3 protein stability, thus strengthening its tumor-suppressive effect." (PMID 40936898, 2025). "In the context of increasing resistance to various conventional targeted therapies, the development of USP38-targeted inhibitors for NSCLC could potentially offer more precise and effective tumor treatments." (PMID 40936898, 2025). "However, current research generally suggests that USP38 regulates the ubiquitination of target proteins at the post-translational modification level, which implies that USP38 may indirectly influence the expression of tumor stemness-related genes by regulating downstream molecules." (PMID 40936898, 2025). "Furthermore, related studies have also found that USP38 effectively promotes vemurafenib-mediated inhibition of downstream molecules such as MMP and LAMP, thereby reducing the migration and invasion capabilities of tumor cells." (PMID 40936898, 2025). "USP38, through its deubiquitinating activity, removes the K63 polyubiquitin chain at the K121 site of HDAC3, enhancing HDAC3’s deacetylation of H3K27 in the promoter regions of tumor stemness-related genes, thereby effectively regulating tumor stem cell properties." (PMID 40936898, 2025).
infection (3 papers, 2021 to 2024). The state of being infected such as from the introduction of a foreign agent such as serum, vaccine, antigenic substance or organism. "A co-immunoprecipitation experiment showed that USP38 bound to the ZIKV E protein, specifically with DI, DII, and C-terminal domain, and attenuated its K48-linked and K63-linked polyubiquitination, thereby repressing infection." (PMID 39273370, 2024). "Mechanistically, USP38 bound to the ZIKV envelope (E) protein through its C-terminal domain and attenuated its K48-linked and K63-linked polyubiquitination, thereby repressed the infection of ZIKV." (PMID 34696459, 2021). "Third, consistent with the research about TRAF3IP3, we constructed the in vivo infection model using mice specifically lack VANGL2 in myeloid cells to verify the harmful role of VANGL2 in vivo, especially in macrophages, which differs from the study about USP38 that used USP38-KO mice." (PMID 37352355, 2023). "Additionally, mutant cells lacking the deubiquitinating activity of USP38 enhanced ZIKV invasion and infection." (PMID 39273370, 2024).
cardiovascular diseases (1 paper, 2024). "However, until now, little attention has been paid to the role of USP38 in cardiovascular diseases." (PMID 38481817, 2024).
inflammation (1 paper, 2023). Aberrant reaction of the microcirculation characterized by movement of fluid and leukocytes from the blood into extravascular tissues. "USP38 knockout reduced atrial inflammation after MI by downregulating the activation of the TAK1-NF-κB pathway, whereas USP38 overexpression showed the opposite effect." (PMID 37953295, 2023). "In the present study, we demonstrated for the first time that USP38, an inflammatory regulatory molecule, can influence atrial inflammation and fibrosis after MI partly through the TAK1/NF-κB signaling pathway." (PMID 37953295, 2023).
USP38 also shares sentences with these, for which no sentence is quoted: Alpha-thalassemia (1 paper); breast carcinoma (1); ciliopathies (1); clear cell renal carcinoma (1); Hypertension (1); hypertrophy (1); immune diseases (1); infarction (1); Klebsiella Infections (1); myocardial infarction (1); ovarian carcinoma (1).